SSH1 (slingshot protein phosphatase 1)
Description:
Protein phosphatase which regulates actin filament dynamics. Dephosphorylates and activates the actin binding/depolymerizing factor cofilin, which subsequently binds to actin filaments and stimulates their disassembly. Inhibitory phosphorylation of cofilin is mediated by LIMK1, which may also be dephosphorylated and inactivated by this protein.
Synonyms: KIAA1298; SSH1L
Tractability: Antibody: its Gene Ontology location is reachable by antibodies, with high confidence. PROTAC: ubiquitination databases record sites on it; its protein half-life has been measured.
Gene: Protein-coding gene on chromosome 12 (108,778,191 to 108,857,613, reverse strand). Ensembl gene ENSG00000084112.
Subcellular location: Cytoplasm, cytoskeleton; Cell projection, lamellipodium; Cleavage furrow; Midbody
Subcellular location (Human Protein Atlas): Plasma membrane; Cytosol; Nucleoplasm
Gene Ontology:
Molecular function: actin binding; phosphoprotein phosphatase activity; protein binding; protein serine/threonine phosphatase activity; phosphatase activity; protein tyrosine phosphatase activity
Biological process: actin cytoskeleton organization; cell morphogenesis; cellular response to ATP; protein dephosphorylation; regulation of protein metabolic process; negative regulation of actin filament polymerization; excitatory chemical synaptic transmission; positive regulation of AMPA glutamate receptor clustering; positive regulation of excitatory postsynaptic potential; positive regulation of synaptic plasticity; positive regulation of vascular associated smooth muscle cell migration
Cellular component: cytoplasm; plasma membrane; cell leading edge; cleavage furrow; cytoskeleton; growth cone; lamellipodium; midbody; synapse
Genetic constraint (gnomAD): Loss-of-function variants: 47 observed, 84.49 expected, observed/expected ratio (o/e) 0.56, 90% interval 0.44 to 0.71. The upper end of that interval is the gene's LOEUF score, 0.71, which puts it in group 2 of 6, group 1 being the genes least tolerant of losing a copy. Missense variants: 1,206 observed, 1,394.6 expected, observed/expected ratio (o/e) 0.86, 90% interval 0.82 to 0.91. Synonymous variants: 599 observed, 553.96 expected, observed/expected ratio (o/e) 1.08, 90% interval 1.01 to 1.16.
Homologues: Orthologues: chimpanzee SSH1 (96% identical), macaque SSH1 (92% identical), dog SSH1 (86% identical), guinea pig SSH1 (85% identical), mouse Ssh1 (83% identical), pig SSH1 (82% identical), rat Ssh1 (82% identical), rabbit SSH1 (80% identical), tropical clawed frog ssh1 (56% identical), zebrafish ssh1a (39% identical), zebrafish ssh1b (39% identical). Paralogues in human: SSH2 (42% identical), SSH3 (24% identical), STYXL2 (12% identical), DUSP16 (12% identical), DUSP8 (11% identical), DUSP6 (10% identical), DUSP7 (10% identical), DUSP9 (9% identical), DUSP10 (9% identical), DUSP4 (9% identical), DUSP1 (9% identical), DUSP5 (9% identical), and 19 more.
Diseases named in the same sentence as SSH1 in open-access papers:
SSH1 is named in the same sentence as 39 diseases in open-access papers, as found by Europe PMC text mining. Sharing a sentence is not in itself a finding about the gene and the disease. The quoted sentences say what the papers report.
breast carcinoma (5 papers, 2012 to 2023). "Aurora Kinase A (AURKA) overexpression has been previously reported to increase the expression of slingshot kinase 1 (SSH1) resulting in increased cofilin activation and migration of breast cancer cells." (PMID 31035605, 2019). "Opposite effects have been reported for cell migration and metastasis of various cancers such as papillary thyroid and breast cancer, where overexpressed AURKA induced an up-regulation of SSH-1 expression, thus favoring the dephosphorylation and activation of CFL1." (PMID 35054947, 2022).
colorectal cancer (5 papers, 2015 to 2023). A primary or metastatic malignant neoplasm that affects the colon or rectum. "Recently, there have been reports indicating that upregulated SSH1 expression was significantly associated with metastasis and strongly correlated with poor prognosis in patients with gastric and colorectal cancers." (PMID 37837551, 2023). "Of note, SSH-family gene expression, mainly SSH1 (Spearman correlation; P = 0.0201) and SSH3 (Spearman correlation; P = 0.0200), was positively and significantly correlated to paladin gene expression in pan-cancer TCGA colorectal cancer patients." (PMID 35882839, 2022).
gastric cancer (4 papers, 2018 to 2021). A primary or metastatic malignant neoplasm involving the stomach. "SSH1 expression level in gastric cancer tissues was significantly associated with lymph node metastasis (P = 0.032)." (PMID 29338701, 2018). "Moreover, SSH-1 was also significantly associated with lymph node metastasis in gastric cancer patients, and was an independent predictor of poor clinical outcomes in Maimaiti’s research." (PMID 31965287, 2020). "SSH1 expression is associated with gastric cancer progression and predicts a poor prognosis." (PMID 29338701, 2018). "SSH1 was reported to be highly expressed in gastric cancer and is correlated to poor clinical outcomes." (PMID 33918195, 2021). "We performed immunohistochemistry (IHC) on tissue microarrays containing 100 gastric cancer specimens to evaluate SSH1 protein expression." (PMID 29338701, 2018). "Multivariate analyses showed that SSH1 was the best predictor of poor prognosis in patients with gastric cancer (P = 0.030)." (PMID 29338701, 2018). "The purpose of this study was to determine whether SSH1 is a key biomarker with prognostic value for survival in patients with gastric cancer." (PMID 29338701, 2018). "SSH1 may play an important role in the development of gastric cancer, and it is a promising target for prevention and/or treatment of gastric cancer." (PMID 29338701, 2018). "Additionally, multivariate regression analysis clearly indicated that SSH1 expression was significantly correlated with poor clinical outcomes of patients with gastric cancer (P = 0.016)." (PMID 29338701, 2018). "We detected the mRNA expression level of three gastric cancer biomarkers, chloride channel-3 (CLC-3), slingshot protein phosphatase 1 (SSH1), and sirtuin 4 (SIRT4) in Cul30-GES-1 and B-GES-1 cells." (PMID 33194715, 2020).
lymph node metastasis (4 papers, 2017 to 2021). "In univariate analysis, parameters such as T grade (P = 0.011), lymphovascular invasion (P = 0.012), and high levels of CFL-1 and SSH1 (P = 0.0125) were significantly correlated with lymph node metastasis risk." (PMID 33482809, 2021). "Conversely, the upregulation of SSH1 mRNA levels has been observed in CRC tumor tissues when compared with control tissues, and was also associated with tumor stage, lymph node metastasis, and poor prognosis." (PMID 33482809, 2021). "To address whether CFL-1 and SSH1 protein levels could be prognostic factors for lymph node metastasis, we performed univariate and multivariate binary logistic regression analyses." (PMID 33482809, 2021).
bladder cancer (1 paper, 2022). "Slingshot homolog-1 (SSH1) had a positive association with tumor grade, tumor invasion, and tumor recurrence of bladder cancer patients." (PMID 35063012, 2022).
bladder tumor (1 paper, 2020). "Immunohistochemistry (IHC) was performed on tissue microarrays composed of 624 bladder UC specimens after transurethral resection of bladder tumor (TUR-BT) to detect SSH-1 expression." (PMID 31965287, 2020).
bladder urothelial carcinoma (1 paper, 2020). "While, the expression and prognostic implications of SSH-1 in bladder urothelial carcinoma (UC) remain unclear and thus were addressed in this study." (PMID 31965287, 2020).
breast tumors (1 paper, 2021). "In breast tumors, SSH1 upregulation was associated with increased metastasis and mortality." (PMID 33482809, 2021).
colon cancer (1 paper, 2022). "Interestingly, SSH1 expression was recently associated with colon cancer progression through regulation of the epithelial to mesenchymal transition." (PMID 35882839, 2022). "Thanks to immunoprecipitation experiments, we demonstrated that paladin, was interacting with SSH1, a phosphatase involved in colon cancer metastasis." (PMID 35882839, 2022).
heart failure (1 paper, 2022). Inability of the heart to pump blood at an adequate rate to meet tissue metabolic requirements. "Methylation at the site cg13033858 would thus enhance fibrosis by downregulating SSH1 biosynthesis, leading to heart failure." (PMID 35292700, 2022).
lymph node tumor (1 paper, 2021). "In fact, patients expressing higher levels of SSH1 exhibited a high percentage of T3 grade (68.7%), and lymph node tumor positivity was associated with the SSH1 IHC score (P = 0.02)." (PMID 33482809, 2021).
neuroblastoma (1 paper, 2026). Neuroblastoma (NB) is the most common solid, extracranial childhood tumor. "Overall, we concluded that the DANCR/miR-125a-5p/ABL2/SSH1/cofilin signaling pathway regulated the metastatic ability of neuroblastoma." (PMID 41602364, 2026). "We verified that DANCR overexpression in neuroblastoma cells significantly enhances the interaction of ABL2 with cortactin, which also affects SSH1-cofilin activity and stabilizes F-actin networks." (PMID 41602364, 2026).
pancreatic neuroendocrine tumor (1 paper, 2024). Pancreatic endocrine tumor, also known as pancreatic neuroendocrine tumor (PNET), describes a group of endocrine tumors originating in the pancreas that are usually indolent and benign, but may have the potential to be malignant. "Administration of Nrp2-blocking antibodies in vivo inhibited tumor vascularity and growth in a mouse model of pancreatic neuroendocrine tumors, repressing F-acting-mediated motility via decreased SSH1-cofilin signaling." (PMID 38592275, 2024). "In addition, vascular expression of Nrp2 promotes angiogenesis and endothelial cell migration in pancreatic neuroendocrine tumors through a VEGF/VEGFR2-independent pathway by activating the SSH1/cofilin/actin axis." (PMID 38592275, 2024).
rectum adenocarcinoma (1 paper, 2021). An adenocarcinoma arising from the rectum. "In according, we found increased methylation level of the CFL-1 and SSH1 promoter regions in colon and rectum adenocarcinoma tissues from the TCGA database, suggesting that differences in the expression of CFL-1 and SSH1 in CRC may be related to epigenetic modifications." (PMID 33482809, 2021).
Sepsis (1 paper, 2024). Sepsis is defined as life-threatening organ dysfunction caused by a dysregulated host response to infection. "A recent study, utilizing both in vitro human endothelial cells and an in vivo mouse model, provided strong evidence that ruscogenin exhibits considerable efficacy in sepsis treatment and blocks specifically MIR-146a-5p and, in parallel, activates NPR2 and SSH1." (PMID 39335561, 2024).
tauopathy (1 paper, 2019). Neurodegenerative disorders involving deposition of abnormal tau protein isoforms (tau proteins) in neurons and glial cells in the brain. "As cofilin activation is largely mediated by the phosphatase SSH1, an enzyme that is also activated by both Aβ and general oxidative stress, we propose that partial inhibition of SSH1 may be a tractable approach to mitigate tauopathy." (PMID 30911686, 2019).
cancer (14 papers, 2015 to 2023). A tumor composed of atypical neoplastic, often pleomorphic cells that invade other tissues. "Cofilin-1 (CFL-1) and its modulators, LIMK1/SSH1, play key roles in mediating the invasiveness by driving actin cytoskeleton reorganization in various cancer types." (PMID 33482809, 2021). "In various cancer types, including gastric, prostate, urothelial, breast, and vulvar, elevated expression of CFL-1 and its regulators, LIMK1/SSH1, have been implicated in tumor progression and aggressiveness, as well as in poor survival rate." (PMID 33482809, 2021). "Inactivation of SSH1 inhibits the dephosphorylation of cofilin, limit actin cytoskeleton reorganization and lamellipodium formation, suppress the metastasis of cancer." (PMID 33614640, 2021). "Another gene included in the signatures and found to be hypermethylated in early BrCa, SSH1, has been presented to be a cancer progression factor." (PMID 33918195, 2021). "During cancer cell migration, SSH1 is identified as a substrate for PKD1-regulation of cofilin activation." (PMID 33123308, 2020). "We found that seven genes (ADPRH, IL1R1, KSR1, SOCS2, JAK1, NFAT5, and SSH1) were more highly expressed in the lower-TMB subtype than in the higher-TMB subtype of more than 10 cancer types." (PMID 30634925, 2019). "The univariate analysis model showed that pathological grade, positive lymph node ratio, size, AJCC stage and SSH1 expression in cancer tissue were important factors for the predication of prognosis in patients with GC." (PMID 29338701, 2018). "SSH1 is the most important factor in cancer cell migration, in our study clarified the clinical significance of SSH1 expression level in GC patients and showed that SSH1 activation plays an important role in GC progression and prognosis." (PMID 29338701, 2018). "In our study, 66 cases of GC tumour tissue (66%) and 66 cases of adjacent-to-carcinoma tissue (82.5%) showed positive SSH1 expression, indicating that SSH1 is expressed at a high frequency." (PMID 29338701, 2018). "SSH1 is the most well-studied cofilin phosphatase which has been found to be upregulated in various invasive cancer cells." (PMID 28025492, 2016). "SSH1-mediated cofilin activation is an essential regulator of actin dynamics; SSH1 and cofilin are highly expressed or highly activated in various malignant tumours, increasing the rate of invasion and metastasis of tumour cells through different mechanisms and pathways." (PMID 29338701, 2018). "It is thus noteworthy that targeting SSH1 strongly suppressed cancer stemness phenotypes, including colony and tumorsphere formation by HCC cells, and may be exploited for the development of a CSCs elimination-based anticancer therapeutic strategy for patients with HCC." (PMID 37837551, 2023). "Importantly, SSH1 dephosphorylates and activates cofilin, and SSH1 may play an important role in cell migration and cancer development through SSH/cofilin pathways." (PMID 29338701, 2018). "In addition, there is evidence suggesting that SSH1 plays an important role in cancer development." (PMID 29338701, 2018). "Research points to slingshot protein phosphatase 1 (SSH1), a modulator of cofilin-1 (CFL-1), as instrumental in the reformation of the actin cytoskeleton, thereby impacting the invasiveness of various cancer types." (PMID 37837551, 2023). "The balance of kinases (LIMK1) and phosphatases (SSH1) can change the activation of cofilin, and LIMK1 and SSH1 have been extensively studied as regulators in cofilin-mediated pathways in cell motility and cancer metastasis." (PMID 33614640, 2021). "However, some of the members participate in the promotion of cancer development, such as STYX, SSH1, and SSH3." (PMID 33053837, 2020). "According to our IHC analysis and microarray data, SSH1 expression was not different between GC and adjacent-to-carcinoma tissues (P = 0.769)." (PMID 29338701, 2018).
cancer (continued). "The difference in SSH1 expression between GC and adjacent-to-carcinoma tissues was not statistically significant (P = 0.769)." (PMID 29338701, 2018). "Besides, SSH-1 positivity predicted a shorter overall survival (OS, p = 0.024), recurrence-free survival (RFS, p < 0.001), progression-free survival (PFS, p = 0.002) and cancer-specific survival (CSS, p = 0.047)." (PMID 31965287, 2020). "However, SSH1 expression in adjacent-to-carcinoma tissues was not significantly correlated with the prognosis of patients with GC in our study (P = 0.095)." (PMID 29338701, 2018).
tumor (9 papers, 2015 to 2025). "The present demonstrated that SSH1 is significantly upregulated in HCC clinical samples, compared to their non-tumor counterpart and this aberrant expression of SSH1 is associated with worse overall and progression-free survival rates." (PMID 37837551, 2023). "SSH-1 positivity was significantly associated with higher pathological grade (p = 0.020), lymphovascular invasion (p = 0.006), tumor recurrence (p < 0.001) and progression (p < 0.001) in bladder UC." (PMID 31965287, 2020). "The presence of SSH-1 in bladder UC specimens was significantly associated with unfavorable clinic-pathological characteristics, including higher pathological grade, lymphovascular invasion, and incidence of tumor recurrence and progression." (PMID 31965287, 2020). "While SSH-1 expression was significantly associated with higher pathological grade (56.55% vs. 47.17%, p = 0.020), lymphovascular invasion (18.94% vs. 10.94%, p = 0.006), and an increased occurrence of tumor recurrence (56.27% vs. 38.11%, p < 0.001) and progression (45.96% vs. 28.68%, p < 0.001)." (PMID 31965287, 2020). "Similar to past studies, SSH1 and RUNX2 were associated with the increased risk of tumor recurrence in our study." (PMID 35063012, 2022). "To confirm the results obtained by bioinformatic analysis, we evaluated CFL-1, LIMK1, and SSH1 mRNA levels by RT-qPCR using tumor tissues from patients with CRC paired with adjacent normal tissues in a clinical cohort." (PMID 33482809, 2021). "When tumor samples were separate into high or low SSH1 expression groups, the SSH1 IHC score was significantly related to lymph node metastasis, similar to CFL-1 data." (PMID 33482809, 2021). "Regarding the clinical and biological significance of CFL-1 and SSH1 in CRC, we found that CFL-1 and SSH1 mRNA levels were downregulated in all tumor stages when analyzed by bioinformatic." (PMID 33482809, 2021). "LIMK1 expression was upregulated (P < 0.0001) whereas CFL-1 and SSH1 were downregulated (P < 0.0001) in all tumor stages when compared with normal tissues." (PMID 33482809, 2021). "CFL-1, LIMK1 and SSH1 mRNA/protein levels were assessed by real-time PCR and immunohistochemical analyses using normal adjacent and tumor tissues obtained from a clinical cohort of CRC patients." (PMID 33482809, 2021). "Multivariate Cox proportional hazard analysis showed that tumor size (p = 0.007), lymphovascular invasion (p = 0.003), recurrence (p < 0.001), progression (p < 0.001) and SSH-1 expression (p = 0.015) were predictors of poor prognosis in bladder UC patients." (PMID 31965287, 2020). "We clarified the clinic-pathological significance of SSH-1 expression in such patients and discovered that SSH-1 was significantly associated with an increased risk of tumor recurrence and progression." (PMID 31965287, 2020). "In present study, we focused on the prognostic significance of SSH-1 expression in stage pT1 bladder UC because patients with this disease after TUR-BT generally suffer from tumor recurrence and progression to invasive cancers." (PMID 31965287, 2020). "SSH1 affects tumour migration by altering cofilin activity, and researchers have proposed studying this interaction to gain better insight into the pathogenesis of digestive system tumours." (PMID 29338701, 2018). "Slingshot homolog-1 (SSH1) plays an important role in pathological processes, including in the occurrence and development of tumours." (PMID 29338701, 2018). "SSH1 was found to be overexpressed in pancreatic cancer (PC) and to contribute to tumour cell migration." (PMID 29338701, 2018). "Moreover, the viability of both HS-SY-II and SSH1 (a primary tumor cell derived from a patient with SS) cells increased progressively with increasing glutamine concentrations from 0 to 4 mM." (PMID 41514527, 2025). "However, further investigation is required to determine the relationship between CFL-1 and SSH1 expression levels and their role in different areas of the tumor." (PMID 33482809, 2021).